RNU6-880P (RNA, U6 small nuclear 880, pseudogene)
Gene: Small nuclear RNA gene on chromosome 1 (42,991,438 to 42,991,544, forward strand). Ensembl gene ENSG00000207256.
Homologues: Orthologues: chimpanzee U6 (97% identical). Paralogues in human: RNU6-25P (92% identical), RNU6-41P (92% identical), RNU6-1 (91% identical), RNU6-15P (91% identical), RNU6-2 (91% identical), RNU6-20P (91% identical), RNU6-35P (91% identical), RNU6-393P (91% identical), RNU6-3P (91% identical), RNU6-48P (91% identical), RNU6-4P (91% identical), RNU6-5P (91% identical), and 1289 more.